CRP (C-reactive protein)
Diseases named in the same sentence as CRP in open-access papers (continued):
Sharing a sentence is not in itself a finding about the gene and the disease.
lymphopenia (continued). "The results of the laboratory showed that lymphocytopenia (79.2%), decreased levels of haemoglobin (77.7%), increased levels of interleukin 6, C-reactive protein, serum ferritin, and D-dimer (77.2%, 55.3%, 55.3%, and 25.9%, respectively), and leukocytopenia (25.9%) were more common." (PMID 35128118, 2022). "However, inflammation parameters (CRP, lymphopenia), LDH—as a tissue injury parameter—and CK were significantly elevated in patients with COVID-19 pneumonia, contrary to normal CXR findings." (PMID 35329864, 2022). "The poor prognosis includes age, comorbidities, severe lymphopenia, high CRP, and dimer D > 1 μg/L." (PMID 36428883, 2022). "Indeed, at the onset of the neurological syndrome, 4 patients had still positive NPS, 6 had thorax imaging findings still suggestive of recent/active pneumonia, 8 still had lymphopenia (<1.500/mm3), and all had still raised CRP." (PMID 35905215, 2022). "Severe lymphopenia, C-reactive protein (CRP), D dimers (>1 μg/L), IL-6, ALT, serum ferritin, lactate dehydrogenase, creatine kinase, troponin are markers with high sensitivity, creatinine, prothrombin time, and procalcitonin being associated with higher mortality." (PMID 36428883, 2022). "The most frequent anomalies that we could observe in this study were the decreased number of white blood cells and lymphopenia, elevated liver-function values and inflammatory markers (CRP and LDH levels) and thrombocytopenia." (PMID 36422104, 2022). "Biological tests revealed lymphopenia (lymphocytes of <1500), high blood creatinine, D-dimer of >500 μg/l, C-reactive protein (CRP) of >130 mg/l, ferritin of >300 μg/l, and lactate dehydrogenase (LDH) of >500 U/l in 78.5%, 33.5%, 82.7%, 47.7%, 77.3%, and 49.7% of the cases, respectively." (PMID 36644046, 2022). "PedSep-C is distinguished by cardiovascular failure and relative absence of need for intubation (14%) with the least pulmonary failure (34%) and need for mechanical ventilation (71%), in the presence of elevated C-reactive protein, high ferritin, and lymphopenia, with 10% mortality." (PMID 35526000, 2022). "He had a lymphopenia (lymph count: 1444), a CRP of 48 mg/L, and an ESR of 25 mm/h." (PMID 35169468, 2022). "Multivariable logistic regression identified age (1.07 (1.02–1.13)), dyspnea (3.56 (1.06–11.96)), high CRP (1.13 (1.03–1.25)), and lymphopenia (6.18 (1.81–21.10)) as the independent predictors for hypoxemia in patients hospitalized for COVID 19 (for all, p < 0.05)." (PMID 35683357, 2022). "Among the maternal outcomes, we found an extremely high case fatality ratio (26.2%) compared with similar studies, associated with the presence of poor prognosis markers such as elevated lactate dehydrogenase, C-reactive protein, ferritin, and D dimer, as well as thrombocytopenia and lymphopenia." (PMID 36471262, 2022). "High IL-6, CRP, ferritin, and D-dimer levels, as well as lymphopenia, are predictors of fatality." (PMID 33550983, 2021). "In conclusion, patients with COVID-like syndrome included in our study displayed a flu-like clinical presentation, including fever, cough, chills, myalgia, and weakness, frequently associated with ground-glass opacities with pneumonia, increased C-reactive protein levels, and lymphopenia." (PMID 34200168, 2021). "Lymphopenia (abnormally low level of lymphocytes in the blood) is common in these patients, and inflammatory markers (C-reactive protein and pro-inflammatory cytokines) could also increase." (PMID 34103090, 2021). "Lymphocytopenia (59%) with elevated CRP (70%) was also common." (PMID 35070470, 2021). "On Day 2, his laboratory findings indicated lymphopenia, neutrophilia, increased C reactive protein (CRP), and raised serum lactate dehydrogenase (LDH); hence, a 7-day course of two antibiotics, meropenem trihydrate (500 mg, thrice daily) and moxifloxacin (400 mg, OD), was also added to the regimen." (PMID 34009133, 2021).
lymphopenia (continued). "Additionally, the worsening radiological features coincide with the worsening of lymphopenia, neutrophilia, CRP elevation and LDH elevation which signify the worsening of systemic inflammation and viral invasion." (PMID 33482780, 2021). "Similarly, laboratory findings that were increased in severe disease included hyperferritinaemia ≥1596 in 25 vs 8%, raised CRP ≥126 in 53 vs 17%, lymphopenia ≤0.5 in 41 vs 23% and hypoalbuminaemia ≤32 in 49 vs 19%." (PMID 34400804, 2021). "In the population we studied, we observed lymphopenia and an increase in CRP and LDH." (PMID 33556140, 2021). "All patients had lymphopenia, mean CRP = 117 mg/l and procalcitonin = 0.23." (PMID 34185186, 2021). "Lymphopenia, positive CRP, and raised LDH were present in 32%, 65%, and 96% of cases, respectively." (PMID 33936224, 2021). "sPD-L1 as well as lymphopenia and elevated levels of CRP could be considered as biomarkers to identify and monitor patients who are likely to benefit from treatment with immune checkpoint inhibitors." (PMID 34163490, 2021). "IL-6 can end the activation of normal T cells, which may be a reason for lymphopenia; robust proinflammatory function; and inducing a variety of acute-phase proteins, such as CRP." (PMID 33602326, 2021). "The laboratory abnormalities including lymphopenia; elevated acute biochemical markers, that is, C-reactive protein; procalcitonin; interleukin-6; D dimer; and radiological findings of ground glassing; pneumonia; and fibrosis are associated with poor prognosis." (PMID 34616572, 2021). "She had mild lymphopenia and granulocytosis, which worsened during hospitalization, slightly increased CRP level 7.15 mg/L (level less than 5 mg/L is considered negative, while a value more than 10 mg/L is suggestive of positive results), and positive PCR for SARS-CoV-2." (PMID 33670394, 2021). "However, cancer patients experienced significantly higher rates of lymphopenia (80% vs. 20%, P = 0.023), high hypersensitive C-reactive protein levels (100% vs. 30%, P = 0.009) and high respiratory rates (>20/min) (80% vs. 25%, P = 0.040)." (PMID 33479506, 2021). "Among the most common laboratory changes, we found increased CRP, lymphopenia, and leukopenia." (PMID 34933389, 2021). "Indeed, patients in treatment group, who were less likely to have elevated IL-6 and CRP level and lymphopenia, had a lower occurrence rate of organ dysfunction and better prognosis." (PMID 33746189, 2021). "Also, the most common laboratory characteristics in SARS-CoV-2 cases were high C-reactive protein (CRP) (58.3%, 95% confidence interval (CI) 21.8–94.7%), lymphopenia (43.1%, 95%CI 18.9–67.3), increased fibrinogen and D-dimer." (PMID 33926382, 2021). "Paraclinical data show leukopenia, lymphopenia, thrombocytopenia, hypoalbuminemia, alarming increase in C-reactive protein (CRP), serum ferritin, aminotransferase, lactate dehydrogenase (LDH), D-dimer and decreased alkaline reserve, and so on, implying a particularly severe immunopathology." (PMID 34066560, 2021). "Lymphopenia, higher CRP levels, elevated ferritin and troponin-T characterized KCG." (PMID 33726806, 2021). "The laboratory tests show normal white blood cell count, lymphopenia, thrombocytopenia and increased values of inflammatory markers (CRP-274.53 mg/L, erythrocyte sedimentation rate-ESR-47mm/L, procalcitonin-2.04 ng/mL, IL-6-113.9 pg/mL, ferritin-3331 ng/mL, fibrinogen 555 mg/dL)." (PMID 33921718, 2021). "Serum ferritin levels of the patient increased, with a further increase in lymphopenia, CRP, and LDH, and as the patient developed signs of cytokine release syndrome (CRS), tocilizumab (80 mg) was administered intravenously with the dose repeated after 12 hours." (PMID 34009133, 2021). "Laboratory findings indicated that the level of CRP and lymphopenia had increased." (PMID 34188437, 2021).
lymphopenia (continued). "Lymphopenia, high concentrations of CRP and LDH may indicate severe acute lung inflammatory reaction and cell damage, which has been reported to be risk factors for severe patients with COVID-1926." (PMID 33536460, 2021). "Blood workup revealed hyperlacticaemia, increased C-reactive protein, and lymphopenia." (PMID 33859884, 2021). "Additionally, lymphopenia (especially of NK cells), leukopenia, and increased levels of inflammatory markers (C-reactive protein, ESR, and pro-inflammatory cytokines - IL-6, TNF-α, IL-8) are recorded, but with normal procalcitonin values." (PMID 32987852, 2020). "In terms of laboratory parameters, a review that included 66 children pointed out normal leucocyte count in 69.2% of the cases, neutropenia in 6%, neutrophilia in 4.6% and lymphopenia in 3%, while C-reactive protein was elevated only in 13.6% of these children." (PMID 33194909, 2020). "In addition, SARS-CoV-2 produces a wide array of laboratory abnormalities, including lymphopenia, elevated c-reactive protein, sedimentation rate, D-dimer, IL-6, and various cytokine elevation." (PMID 33501389, 2020). "Additionally, we found that severe lymphocytopenia, elevated ferritin, and CRP were correlated with disease severity, which was affirmed in our transplant recipient." (PMID 32770646, 2020). "Laboratory findings: any decreased WBC count, lymphopenia, and/or elevated CRP." (PMID 33224906, 2020). "Eight (16%) patients had lymphopenia, seven (14%) with thrombocytopenia, four (8%) with lymphocytosis, two (4%) with thrombocytosis, ten (20%) with elevated C-reactive protein, four (8%) with hemoglobin above, and six (12%) with below standard reference values." (PMID 32370747, 2020). "Early reports from the Chinese province of Hubei described some predictive biomarkers for the clinical outcome of hospitalised patients, namely lymphopenia and the elevation of D-dimer, ferritin, interleukin 6 (IL-6), troponin and myoglobin, C-reactive protein (CRP) and lactate dehydrogenase (LDH)." (PMID 32605582, 2020). "The present study revealed that the development of new pulmonary lesions during treatment was common, and was mainly related to lymphopenia, elevated CRP, or primary lesions progression, but irrelevant to the extent of primary lesions and other clinical characteristics." (PMID 32922203, 2020). "Previous studies of severe cases had reported normal/or increased white blood cell count, leucopoenia, lymphopenia, increased haemoglobin level, decreased albumin, increased lactase dehydrogenase, increase CRP, increase D-dimer, aspartate aminotransferase (AST) and alanine aminotransferase (ALT)." (PMID 33456651, 2020). "In the presence of “elevated ESR and/or CRP and at least 1 other suggestive laboratory feature (lymphopenia, neutrophilia, thrombocytopenia, hyponatremia, or hypoalbuminemia),” the next tier of investigations (ferritin, d-dimer, PT, PTT, fibrinogen, troponin I, NT-pro-BNP) should be performed." (PMID 33859967, 2020). "Regarding our results, higher lymphopenia level was found in the severe cases, but the assessment of the prognosis value of the biological parameters in correlation with the severity of the disease demonstrated that CRP level was more relevant." (PMID 33312067, 2020). "Worse OS was associated with high mean thoracic RT dose, high CRP/Albumin, large tumor volume and corticosteroids use (p < 0.05, univariate analysis), but not with lymphopenia ≥ G3." (PMID 32181373, 2020). "Most patients demonstrated lymphopenia with marked CRP and D-dimer increases and albumin decreases." (PMID 33102532, 2020). "C-reactive protein was ≥ 100 mg/L in 445 (44.7%) patients and lymphopenia was common (618, 60.9%)." (PMID 33272355, 2020).
lymphopenia (continued). "Laboratory findings, as well, appeared analogous to the ones described in non-pregnant SARS-CoV-2-infected patients: elevated levels of C-reactive protein (48%), mild lymphocytopenia (29%), and elevated levels of liver transaminase (8%) were the most frequently recorded abnormalities." (PMID 32570959, 2020). "Indeed, neutrophilia and lymphopenia (resulting in an increased neutrophil to lymphocyte ratio), increased systemic interleukin-6 (IL-6) and C-reactive protein (CRP), correlate with incidence of intensive care admission and mortality." (PMID 32943497, 2020). "Even though the cause of death in our cohort was mostly due to progressive disease imitated in corticosteroid use and high CRP/Albumin, assessing the effect of treatment-related lymphopenia on survival in patients with better prognosis at early stage of lung cancer is encouraging." (PMID 32181373, 2020). "Lymphopenia, elevated C-reactive protein, and elevated interleukin-6 were found upon admission." (PMID 33058760, 2020). "Through univariate logistic regression models, we found that advanced age (≥65 years old), chronic comorbidities, lymphocytopenia, elevated hs‐CRP, increased D‐dimer, and elevated levels of ALT were the key risk factors for the progression of COVID‐19 patients into their severe stage." (PMID 32893398, 2020). "We found that absolute lymphopenia and elevated CRP levels immediately before treatment with TCZ could reliably distinguish survivors from those patients who died." (PMID 33089038, 2020). "Age, viral load, lung injury score, and albumin, CRP, LDH, LYM (%), LYM, and NEU (%), may be predictors of disease severity, and lymphopenia is linked to the increased severity, mortality and dysregulated immunological response." (PMID 32746805, 2020). "Additionally, lymphopenia, thrombocytopenia, and elevated C-reactive protein, procalcitonin, and lactate dehydrogenase levels are frequently observed." (PMID 32351920, 2020). "In addition, patients with lymphopenia had increased mean levels of ferritin, CRP, fibrinogen, D dimer, procalcitonin, and troponin I." (PMID 33324414, 2020). "The laboratory tests pointed out lymphopenia (940/μL), thrombocytopenia (136,000/μL), a neutrophile count within the normal ranges (3,010/μL), a normal leukocyte count (7,910/μL), elevated lactate dehydrogenase (776 U/L), and a CRP of 4.1 mg/L." (PMID 33194909, 2020). "Lymphopenia was also associated with worse survival in multivariable models, including traditional clinical risk factors, and this risk intensified when accompanied by bone marrow dysregulation (elevated RDW) and/or inflammation (elevated CRP level)." (PMID 31790569, 2019). "Comparative analysis of the baseline variables between patients with and without infection revealed that patients in the infection group were more likely to have high serum LDH, KL-6, CRP and hypoalbuminemia, lymphopenia, hypocapnia, and high ILD score, especially in the upper lung fields." (PMID 29325580, 2018). "The neutrophil/lymphocyte count ratio (NLCR) has been introduced as a parameter for systemic inflammation in critically ill patients and was found, together with lymphocytopenia, to be a better predictor of bacteraemia than routine parameters like C-reactive protein and total leukocyte count." (PMID 23506136, 2013). "Therefore we tested the consequence of neutropenia, lymphopenia, monopenia and eosinopenia on CRP elevation in bacteremic NICU patients." (PMID 24244325, 2013). "Some viruses infect lymphocytes and by increasing their destruction, it causes lymphopenia and a decrease in serum albumin, which is a negative acute-phase reactant, while it causes an increase in the levels of CRP and ferritin, which are positive acute-phase reactants." (PMID 40956850, 2025).
lymphopenia (continued). "This transition mirrors immunological shifts: CRP production is more robust in older children due to enhanced hepatocyte response to IL-6, while lymphopenia (integrated in CALLY) may be less specific in bacterial/viral co-infections prevalent in this age group." (PMID 41321450, 2025). "In addition, greater inflammatory alterations (increased c-reactive protein and ferritin), alteration of liver enzymes, hematological alterations (lower hemoglobin, lymphopenia and mild thrombocytopenia) and coagulation alterations (fibrinogen and D-dimer) were found in this group of patients." (PMID 39442113, 2024). "A proportion of CCI patients may develop persistent inflammation, immunosuppression, and catabolism syndrome (PICS) with persistent inflammation [e.g., high C-reactive protein (CRP)], immunosuppression (e.g., lymphocytopenia), and catabolism (e.g., low albumin)." (PMID 39479266, 2024). "Similarly, multiple studies suggested that lymphocytopenia, including low CD3+ T cell levels, along with elevated inflammatory markers such as serum ferritin and high-sensitivity C-reactive protein, increased the risk of acute respiratory distress syndrome (ARDS) development and poor prognosis." (PMID 39519310, 2024). "However, the level of CRP has been shown to rise earlier than either lymphopenia or neutrophilia." (PMID 37089472, 2023). "However, age, sex, course of disease, leukopenia, lymphopenia, C- reactive protein and hypoproteinemia were not the risk factors associated with IFI in patients with SLE." (PMID 36930103, 2023). "Maybe in our study increased CRP levels and lymphopenia can complain with these hypotheses." (PMID 37942197, 2023). "In addition, lymphopenia, C-reactive protein and hypoproteinemia are also non-risk factors in SLE complicated with IFI." (PMID 36930103, 2023). "We, similarly to others, confirmed that leucocytosis, neutrophilia, lymphocytopenia, thrombocytopenia, increased CRP, PCT, ferritin, LDH, D-dimer, and IL-6 levels, as well as impaired oxygenation are suitable indicators for MIS, and might be associated with worse clinical outcomes." (PMID 36830885, 2023). "Serum LDH levels could be an adjunctive diagnostic biomarker for non-HIV-PJP, and elevated serum D-dimer and C-reactive protein and lymphopenia are reported to be associated with the prognosis of PJP patients." (PMID 36552932, 2022). "In addition, only the second patient recorded laboratory changes represented in the first infection with a slight decrease in the lymphocyte count of 1500 with a decrease in platelets 128,000 and a slight rise in CRP 7.2 with an obvious lymphopenia of 800 in the second infection." (PMID 36117528, 2022). "In addition, high CRP and BUN level and lymphopenia were associated with poor prognosis." (PMID 34945730, 2021). "Moreover, we found higher white blood cell counts, lactate dehydrogenase levels and CRP levels and more marked lymphopenia in patients with the involvement of more lung zones, which may suggest severe SARS-CoV-2 infection." (PMID 33390795, 2021). "Furthermore, a newly published meta-analysis showed that, lymphopenia, decreased albumin, increased level of C-reactive protein (CRP) and Erythrocyte sedimentation rate (ESR), as well as Lactate dehydrogenase (LDH), seemed to be the most common abnormal laboratory findings." (PMID 32788884, 2020). "Moreover, due to the impact of the tumor itself and treatment-related factors, laboratory tests of patients with RIDI may show signs of inflammation, such as an increased white blood cell, marked lymphopenia, CRP and PCT14." (PMID 33029098, 2020). "Therefore, we aimed to test whether the presence of lymphopenia may modify the response to corticosteroids (mainly in C reactive protein (CRP)) in patients with severe CAP and high inflammatory status)." (PMID 31540339, 2019).